USP35 (ubiquitin specific peptidase 35)
Description:
Deubiquitinase that plays a role in different processes including cell cycle regulation, mitophagy or endoplasmic reticulum stress. Inhibits TNFalpha-induced NF-kappa-B activation through stabilizing TNIP2 protein via deubiquitination. Plays an essential role during mitosis by deubiquitinating and thereby regulating the levels of Aurora B/AURKB protein. In addition, regulates the protein levels of other key component of the chromosomal passenger complex (CPC) such as survivin/BIRC5 or Borealin/CDCA8 by enhancing their stability. Regulates the degradation of mitochondria through the process of autophagy termed mitophagy.
Synonyms: KIAA1372
Tractability: PROTAC: UniProt records ubiquitination sites on it; ubiquitination databases record sites on it; its protein half-life has been measured.
Target class: Enzyme; Hydrolase
Gene: Protein-coding gene on chromosome 11 (78,188,812 to 78,215,232, forward strand). Ensembl gene ENSG00000118369.
Subcellular location: Cytoplasm; Mitochondrion
Subcellular location (Human Protein Atlas): Nucleoli fibrillar center; Nucleoplasm
Gene Ontology:
Molecular function: cysteine-type deubiquitinase activity
Biological process: protein deubiquitination
Cellular component: cytoplasm; mitochondrion
Genetic constraint (gnomAD): Loss-of-function variants: 69 observed, 77.92 expected, observed/expected ratio (o/e) 0.89, 90% interval 0.73 to 1.08. The synonymous counts are far from expectation, so gnomAD's model fits this gene poorly and the ratio says little. Missense variants: 1,502 observed, 1,287 expected, observed/expected ratio (o/e) 1.17, 90% interval 1.12 to 1.22. Synonymous variants: 714 observed, 548.37 expected, observed/expected ratio (o/e) 1.3, 90% interval 1.22 to 1.38.
Homologues: Orthologues: chimpanzee USP35 (99% identical), macaque USP35 (97% identical), dog USP35 (91% identical), pig USP35 (90% identical), mouse Usp35 (89% identical), rat Usp35 (89% identical), guinea pig USP35 (85% identical), rabbit USP35 (80% identical), tropical clawed frog usp35 (56% identical). Paralogues in human: USP38 (44% identical), USP34 (20% identical), USP24 (18% identical), USP9X (17% identical), USP9Y (16% identical), USP19 (15% identical), USP32 (15% identical), USP4 (15% identical), USP8 (14% identical), USP11 (14% identical), USP15 (14% identical), USP31 (13% identical), and 59 more.
Diseases named in the same sentence as USP35 in open-access papers:
USP35 is named in the same sentence as 26 diseases in open-access papers, as found by Europe PMC text mining. Sharing a sentence is not in itself a finding about the gene and the disease. The quoted sentences say what the papers report.
lung carcinoma (21 papers, 2015 to 2026). "Here, we focus on delineating the roles and underlying mechanisms of USP35 in non‐small cell lung cancer (NSCLC)." (PMID 34618999, 2022). "We further evaluated the effect of USP35 silence on the chemosensitivity of lung cancer cells to DDP and PTX, and found that USP35‐deficient lung cancer cells are more sensitive to DDP and PTX chemotherapy." (PMID 33931967, 2021). "Overall, our data prove that USP35‐deficient lung cancer cells are more sensitive to chemotherapeutic drugs." (PMID 33931967, 2021). "In addition, under ferroptosis activator Erastin or RSL3 stimulation, knocking down USP35 can cause iron metabolism disorder and pig ferroptosis of lung cancer cells, thus promoting the growth of lung cancer cells and tumor progression." (PMID 38666028, 2024). "For example, ubiquitin-specific protease 35 (USP35), a deubiquitinase, when overexpressed in lung cancer cells, stabilizes ferroportin and prevents ferroptosis, thus promoting cell proliferation." (PMID 39917300, 2025). "In contrast, inhibiting USP35 expression leads to an increase in ferroptosis and a suppression of lung cancer cell proliferation." (PMID 39917300, 2025). "Functionally, knocking down USP35 in lung cancer cells can directly promote ferroptosis by down-regulating FPN protein levels and inhibiting cell growth and clone formation." (PMID 38666028, 2024). "Studies have shown that USP35 is significantly overexpressed in human lung cancer cells and tissues, and USP35 can maintain the stability of FPN protein by targeting FPN." (PMID 38666028, 2024). "USP35 also facilitates the growth and progression of lung cancer cells by desensitizing them from ferroptosis through deubiquitination of ferroportin." (PMID 37993419, 2023). "Knockdown of USP35 can inhibit the progression of lung cancer, promote ferroptosis, and increase the sensitivity of lung cancer cells to cisplatin and paclitaxel chemotherapy." (PMID 37005430, 2023). "Previous studies have demonstrated the therapeutic potential of USP35 in some types of cancers, such as lung cancer, ovarian cancer, and breast cancer." (PMID 36864055, 2023). "It has been demonstrated that deubiquitinase USP35 is overexpressed in human lung cancer tissues and cell lines." (PMID 35155264, 2022). "Ribosome‐binding protein 1 (RRBP1) was found to positively correlate with ubiquitin‐specific protease 35 (USP35) levels by proteomic analysis, which was validated in genetically modified cells and human non‐small cell lung cancer (NSCLC) tissues." (PMID 34618999, 2022). "Both H460 and H1299 cells have high basal USP35 expression, we then checked the effect of USP35 overexpression in normal cells and USP35 low expressing lung cancer cells." (PMID 33931967, 2021). "The present study identify the role and potential molecular basis of USP35 on ferroptosis in lung cancer cells." (PMID 33931967, 2021). "Consistently, USP35 lost its motivated effects on cell viability and colony formation upon erastin stimulation in lung cancer cells with shFPN infection." (PMID 33931967, 2021). "Accordingly, USP35 mRNA levels were also highly expressed in lung cancer cell lines (A549, H358, H460, H1299, and H1650) compared to the normal BEAS‐2B and HBE lung epithelial cell lines." (PMID 33931967, 2021). "USP35 is abundant in human lung cancer tissues and cell lines compared with the ANT or normal lung epithelial cells." (PMID 33931967, 2021). "Consistently, we herein found that USP35 silence promoted ferroptosis of lung cancer cells, thereby sensitizing them to DDP and PTX chemotherapy in vivo and in vitro." (PMID 33931967, 2021). "In the current study, we also detected a high USP35 expression in human lung cancer tissues and cell lines." (PMID 33931967, 2021). "Depletion of USP35 can promote ferroptotic cell death and sensitivity to cisplatin and paclitaxel chemotherapy in lung cancer cells." (PMID 34796174, 2021).
lung carcinoma (continued). "In this research, we aim to elucidate the potential role and molecular basis of USP35 in lung cancer." (PMID 33931967, 2021). "USP35 modulates ferroptosis in lung cancer via targeting FPN, and it is a promising therapeutic target to lung cancer." (PMID 33931967, 2021). "To clarify the role of USP35 in the pathogenesis of lung cancer, we silenced USP35 in H460 and H1299 cells, and the efficiency was determined by IB data." (PMID 33931967, 2021). "In contrast, knockdown of endogenous USP35 expression increased intracellular iron levels and provoked ferroptosis to inhibit lung cancer cell growth, colony formation and tumor progression." (PMID 33931967, 2021). "USP35 knockdown promoted ferroptosis, and inhibited cell growth, colony formation, and tumor progression in lung cancer cells." (PMID 33931967, 2021). "More importantly, we observed that USP35 knockdown sensitized lung cancer cells to cisplatin and paclitaxel chemotherapy." (PMID 33931967, 2021). "USP35 is abundant in lung cancer cells and acts as a deubiquitinase to maintain the protein stability of ferroportin, which is a cellular efflux channel for iron." (PMID 34796174, 2021). "All the findings identify a critical role of USP35 in regulating lung cancer cell growth and tumor progression." (PMID 33931967, 2021). "18/22 (81.8%) of the clinical breast cancer specimens and 9/11(81.8%) of the lung cancer specimens had lower USP35 mRNA levels than adjacent normal tissues." (PMID 26348204, 2015). "Therefore, we conclude that ferroptosis contributes to USP35 knockdown‐induced cell death in lung cancer cells." (PMID 33931967, 2021). "Lung cancer cells were infected with lentiviral vectors to silence or overexpress USP35." (PMID 33931967, 2021). "We next explored whether USP35 regulated cell growth and tumor progression by affecting the lung cancer cell cycle." (PMID 33931967, 2021). "Besides, the activation of PI3K‐AKT and MEK1/2‐ERK1/2, two important cancer signaling pathways, was also unchanged by USP35 silence in lung cancer cells." (PMID 33931967, 2021). "USP35 was abundant in human lung cancer tissues and cell lines." (PMID 33931967, 2021). "USP35 modulates iron homeostasis and ferroptosis in lung cancer tissues and cell lines." (PMID 33931967, 2021). "Moreover, USP35 knockdown sensitizes lung cancer cells to DDP and PTX chemotherapy, defining USP35 as a promising therapeutic target to lung cancer." (PMID 33931967, 2021). "We first detected the alteration of USP35 abundance in lung cancer tissues and cell lines." (PMID 33931967, 2021). "Of note, EGFR‐mutated lung cancer cells (eg, H1650 cell) are more sensitive to TKI, and we thus evaluated whether USP35 silence would sensitize H1650 cell to GFB chemotherapy." (PMID 33931967, 2021). "However, our result is in contrast with a previous report, which showed that USP35 inhibited the growth of lung cancer cells by stabilizing the ABIN-2." (PMID 34131114, 2021). "Given the high expression of USP35 in lung cancer cells and its role in regulating ferroptosis, we finally evaluated whether USP35 silence could sensitize lung cancer cells to the chemotherapeutic drugs." (PMID 33931967, 2021). "USP35 is abundant in human lung cancer tissues and cell lines." (PMID 33931967, 2021). "Ubiquitin‐specific protease 35 (USP35) is a deubiquitinase that is overexpressed in lung cancer, and its knockdown, in addition to promoting ferroptosis and chemotherapeutic sensitivity to cisplatin and paclitaxel, inhibits lung cancer cell growth, colony formation, and tumor progression." (PMID 34926310, 2021). "Yet, the potential role and molecular basis of USP35 in lung cancer remain unclear." (PMID 33931967, 2021). "Following the observation of altered expression levels of USP35, USP36, USP37, USP47, USP49, and OTUD6B in response to cisplatin treatment in lung cancer cells, both at the mRNA and protein levels, we sought to explore their significance in lung cancer." (PMID 41399373, 2026).
lung carcinoma (continued). "Multiplex RT-PCR showed distinct mRNA expression profiles of several DUB genes, including USP35, USP36, USP37, USP47, USP49, and OTUD6B in A549 lung cancer cells following exposure to cisplatin." (PMID 41399373, 2026). "DUB ubiquitin-specific protease 35 (USP35) interacts with SLC40A1 and maintains its protein stability to prevent iron overload and ferroptosis in lung cancer cells." (PMID 36551253, 2022). "We performed IHC using specific antibodies against USP35 and RRBP1 on 45 lung cancer tissue samples." (PMID 34618999, 2022). "While USP35 knockdown increases intracellular LIP levels and ferroptosis via decreasing FPN‐mediated iron export, accompanied by the decreases of lung cancer cell growth, colonization and tumor formation, and the increases of chemosensitivity to DDP and PTX." (PMID 33931967, 2021). "Knockdown of USP35 facilitates FPN ubiquitination and degradation, and decreases FPN‐dependent iron export, thereby triggering iron overload and ferroptosis in lung cancer cells." (PMID 33931967, 2021). "Correspondingly, the nude mice inoculated with CTRL lung cancer cells had decreased tumor volumes and weights after erastin or RSL3 treatment; however, these tumor suppressive effects were blocked with USP35 overexpression." (PMID 33931967, 2021). "Meanwhile, knockdown of USP35 enhanced the sensitivity of lung cancer cells to cisplatin and paclitaxel by targeting FPN1 in lung cancer." (PMID 34858857, 2021). "Collectively, our data prove that USP35 is required for FPN protein stability and the iron export in lung cancer cells, thereby preserving intracellular iron homeostasis and tumor growth." (PMID 33931967, 2021). "In lung cancer cell, proteasomal degradation of SLC40A1 is inhibited by ubiquitin specific peptidase 35 (USP35), which is a deubiquitinating enzyme that is abnormally expressed in many cancers." (PMID 34742351, 2021). "In lung cancer, knockdown of ubiquitin‐specific proteases(USP35) promotes FPN1 ubiquitination and degradation, and FPN-dependent cellular iron exclusion is reduced, thereby triggering iron overload and ferroptosis in lung cancer cells." (PMID 35990689, 2022). "Meanwhile, knockdown of USP35 can promote the degradation of FPN in lung cancer cells and reduce iron exportability that makes cancer cells sensible to ferroptosis, enhancing the chemotherapy effect on lung cancer cells." (PMID 35155264, 2022). "Such USP35 abundance did not affect lung cancer cell growth, colonization, and tumor formation under basal conditions, but prevented erastin/RSL3‐elicited ferroptosis and tumor‐suppressive effects." (PMID 33931967, 2021). "verified that USP35 could maintain the stability of its protein by deubiquitinating FPN1, and reduce the iron disorder triggered by erastin/RSL3, thereby promoting lung cancer cell growth and tumor progression." (PMID 34858857, 2021). "Besides, we observe that USP35 overexpression does not affect ferroptosis and tumor progression under basal conditions, but results in an alleviation on erastin/RSL3‐caused iron disturbance and ferroptosis, accompanied by the increased lung cancer cell growth and tumor progression." (PMID 33931967, 2021). "USP35 overexpression decreased intracellular LIP and Fe2+ in lung cancer cells upon ferroptotic stimulation, yet failed to do so in FPN‐deficient cells." (PMID 33931967, 2021). "The expression of USP35 also decreased in MCF7 and BT474 breast cancer cells as well as in H1299 and A549 lung cancer cells compared with that in non-malignant breast epithelial cells MCF10A and that in lung epithelial cells BEAS-2B." (PMID 26348204, 2015). "Substantiating these findings, western blotting analysis confirmed the protein expression levels of USP35, USP36, USP37, USP47, USP49, and OTUD6B in cisplatin-treated lung cancer cells, mirroring the mRNA trends observed in non-treated counterparts except for OTUD6B." (PMID 41399373, 2026).
lung carcinoma (continued). "Of note, USP35 overexpression fails to affect tumorigenesis and ferroptosis under basal conditions, but reduces erastin/RSL3-triggered iron disturbance and ferroptosis, thereby facilitating lung cancer cell growth and tumor progression." (PMID 36551253, 2022). "USP35 overexpression did not affect tumorigenesis and ferroptosis under basal conditions, but reduced erastin/RSL3‐triggered iron disturbance and ferroptosis, thereby facilitating lung cancer cell growth and tumor progression." (PMID 33931967, 2021).
ovarian carcinoma (12 papers, 2021 to 2025). A malignant neoplasm originating from the surface ovarian epithelium. "While USP35‐deficient ovarian cancer cells were sensitized to DDP chemotherapy." (PMID 33931967, 2021). "Besides, deubiquitinase USP35 could restrain STING-mediated interferon signaling in ovarian cancer, highlighting the potential associations between USP35 and CD8+ T cell infiltrations." (PMID 36357379, 2022). "Some studies have confirmed that patients with high USP35 expression in ovarian cancer, liver cancer, clear cell renal cell carcinoma, and cutaneous melanoma have a poor prognosis." (PMID 41372134, 2025). "Deubiquitinase USP35 inhibits STING-mediated interferon signaling in ovarian cancer by binding to and deubiquitinating STING, preventing its activation." (PMID 39949780, 2025). "An additional USP that has revealed promising features as a therapeutic target in ovarian carcinoma is USP35." (PMID 39430244, 2024). "While some studies suggest that Usp35 is a tumor suppressor, others point to an upregulation of Usp35 in ovarian cancer." (PMID 38242896, 2024). "More recently, USP35 has been reported to play oncogenic roles in ovarian cancer through targeting stimulator of interferon genes (STING) pathway." (PMID 34618999, 2022). "In contrast, a recent study revealed that USP35 is overexpressed in ovarian cancer with poor prognosis." (PMID 34131114, 2021). "However, in ovarian cancer, USP35 is upregulated, leading to STING inactivation and immune suppression." (PMID 39949780, 2025). "For example, USP35 promotes ovarian cancer development by deubiquitinating and inactivating STING." (PMID 37993419, 2023). "Besides, USP35 has been shown to be upregulated in ovarian cancer and contribute to chemoresistance via activating STING‐TBK1‐IRF3 pathway." (PMID 34618999, 2022). "Literature reports have also confirmed that in ovarian cancer, USP35 can directly de-ubiquitinate and inactivate STING, thereby enhancing the chemoresistance of ovarian cancer cells to chemotherapy drugs and promoting tumor development." (PMID 41372134, 2025). "USP35 via deubiquitination and inactivation of STING restrains the activation of the STING-TBK1-IRF3 pathway and type I interferon production, important for enhancing anti-tumor immunity, in ovarian cancer cells." (PMID 34131114, 2021).